USP14 (ubiquitin specific peptidase 14)
Diseases named in the same sentence as USP14 in open-access papers (continued):
Sharing a sentence is not in itself a finding about the gene and the disease.
viral infection (13 papers, 2012 to 2025). "Dysregulation of USP14 causes pathological conditions, such as cancer, neurodegenerative disease, autophagy, immune responses, and viral infections." (PMID 35069211, 2021). "As a proteasome-associated DUB, USP14 has been shown to regulate numerous cellular processes, including cell cycle, DNA repair, epigenetics, autophagy, neuropathies, immunity, viral infection, and tumorigenesis." (PMID 30254335, 2018). "The post-translational modification process induced by the dysregulation of USP14 is involved in the onset and progression of tumors, immune responses, and viral infections through the modulation of multiple signaling pathways." (PMID 38658954, 2024). "Upon viral infection, the ISG tripartite motif 14 (TRIM14) directly binds to the C-terminus of cGAS and recruits ubiquitin-specific peptidase 14 (USP14) to prevent K48-linked ubiquitination and degradation of cGAS." (PMID 38660307, 2024). "USP14 disorders lead to several pathological conditions, including viral infections, hepatosteatosis, neuroglial diseases, and cancers." (PMID 37046655, 2023). "USP14 has been shown to act a crucial part among various innate immune processes, such as viral infection and inflammatory response." (PMID 37658402, 2023). "Increasing evidence have shown that USP14 is involved in several canonical signaling pathways, correlating with cancer, neurodegenerative diseases, autophagy, immune responses, and viral infections." (PMID 35069211, 2021). "Therefore, we concluded that miR-30a enhances type I IFN antiviral signaling to inhibit viral infection through the miR-30a-USP14-RIG-I ubiquitination axis." (PMID 40662581, 2025). "In this study, we demonstrated that miR-30a specifically inhibited USP14 expression by binding to the USP14 3′UTR, thereby promoting RIG-I K63-linked ubiquitination and enhancing RIG-I-mediated type I IFN antiviral signaling against viral infection." (PMID 40662581, 2025). "In addition to its role in the immune response, USP14 also plays an important role in viral infections, inflammation, tumors, autophagy, and neurodegenerative disorders." (PMID 38699234, 2024). "Inhibition of USP14 induces the K63-linked ubiquitination of PRV VP16, where USP14 directly binds to ubiquitin chains on VP16 through its UBL domain during the early stage of viral infection." (PMID 35336954, 2022). "Inhibiting USP14 in turn results in RIG-I-triggered TNF-α and IL-6 production in mice with virus infection." (PMID 37658402, 2023). "In summary, these results demonstrated that WP1130 binds and inhibits USP14 in murine macrophages independent of virus infection." (PMID 22792064, 2012). "Moreover, USP14 has been shown to bind to the inositol-requiring enzyme, a mediator of the UPR, which is activated by ER stress induced by the production of large amounts of viral proteins after viral infection." (PMID 35069211, 2021). "Taken together, these results demonstrated that USP14 activity is inhibited by WP1130 in RAW cells without affecting total protein levels, and that USP14 activity and WP1130 inhibition of this activity is independent of viral infection." (PMID 22792064, 2012).
Ataxia (12 papers, 2012 to 2023). Ataxia refers to impaired coordination of voluntary muscle movement. "In neurological systems, USP14 was reported to regulate long-term memory formation, while alteration of USP14 contributes to loss-of-mobility and early postnatal lethality in ataxia (axJ) mice." (PMID 30425250, 2018). "A role for USP14 in the nervous system was first demonstrated by the identification of a recessive mutation in the Usp14 gene, which causes ataxia in the axJ mouse line." (PMID 25191222, 2014). "Finally, a spontaneous mutation in the Usp14 gene, encoding the proteasome-associated deubiquitinating enzyme USP14, leads to progressive locomotor defects and ataxia." (PMID 32719102, 2020). "We previously showed that loss of USP14 in ataxia (axJ) mice results in reduced ubiquitin levels, motor endplate disease, Purkinje cell axonal dystrophy and decreased hippocampal paired pulse facilitation (PPF) during the first 4-6 weeks of life, and early postnatal lethality by two months of age." (PMID 24358326, 2013). "However, loss of USP14 in the spontaneously occurring ataxia mouse mutant leads to a dramatic neuromuscular phenotype and early perinatal lethality, suggesting that USP14 inhibition may have adverse consequences in the nervous system." (PMID 25575639, 2015). "The ataxia mice axJ, with a loss-of-function mutation in the UPS-associated deubiquitinating enzyme Usp14 show severe defects of the neuromuscular junction with impaired presynaptic function which are rescued by restoration of intracellular ubiquitin levels." (PMID 30618634, 2018). "Genetic background can have a profound effect on symptoms and progression of ataxia in Usp14-mutant mice." (PMID 25191222, 2014). "In mice, defective USP14 results in ataxia and abnormal synaptic transmission and USP14 is unique among those known USPs in that it is activated catalytically upon specific association with the 26S proteasome." (PMID 23702845, 2013). "Disruption of two components of the UPS, tripartite motif protein 2 (Trim2GT) mice and ubiquitin-specific protease 14 (Usp14) (axJ mice), resulted in phenotypic ataxia resulting from motor neuron dysfunction." (PMID 22570767, 2012). "Most of what we know about USP14 in synapse development and function comes from analysis of the ataxia (axJ) mutant mouse." (PMID 23316392, 2012). "Mutation of several ubiquitin ligases and DUBs is linked to neurological diseases, including Parkin and UCH-L1 in Parkinson's Disease, Ube3A in Angelman's Syndrome, and USP14 in ataxia." (PMID 23316392, 2012). "USP14/Ubp6 is dynamically associated with the 19S RP through its ubiquitin-like (UBL) domain, not essential for cell survival, but important for ubiquitin recycling in budding yeast and a spontaneous ataxia mouse strain." (PMID 31703099, 2019). "Mice expressing catalytically inactive USP14 in the nervous system exhibited motor deficits, altered NMJ structure, and synaptic transmission deficits that were similar to what is observed in the USP14-deficient ataxia mice." (PMID 25575639, 2015). "Moreover, restoration of neuronal Usp14 levels (Thy1-Usp transgene) in axJ mice alleviated phenotypic ataxia and NF accumulations." (PMID 22570767, 2012). "Importantly, neuron-specific expression of Usp14 also restored cellular monomeric ubiquitin to wild type levels, confirming the role of this proteasome-associated DUB in governing ubiquitin homeostasis and supporting a presynaptic role for USP14 in the ataxia phenotype of the axJ mice." (PMID 23316392, 2012). "The ataxia phenotype in the axJ mice suggests that the cerebellum is negatively affected by nearly absent USP14." (PMID 25191222, 2014).
non-small cell lung carcinoma (11 papers, 2013 to 2026). A group of at least three distinct histological types of lung cancer, including non-small cell squamous cell carcinoma, adenocarcinoma, and large cell carcinoma. "In non-small cell lung cancer, USP14 is a regulator of major double-stranded break repair pathways under the ionizing radiation treatment to avoid lung tumor death." (PMID 37686660, 2023). "MiR-124a targets USP14 to hinder stemness and promotes gefitinib sensitivity in non-small cell lung cancer cells." (PMID 32908134, 2020). "The USP14 expression is upregulated in non-small cell lung cancer (NSCLC) cells, especially in adenocarcinoma cells, suggesting its tumor-promoting function." (PMID 26097878, 2015). "USP14 mRNA levels in different non-small cell lung cancer (NSCLC) cell lines were detected by real-time qPCR." (PMID 23702845, 2013). "In addition, a tumor suppressive miR-124-3p was identified to inhibit the self-renewal of non-small-cell lung cancer cells as a consequence of targeting ubiquitin specific peptidase 14 (USP14), which is a positive regulator of β-catenin expression." (PMID 31861937, 2019). "Previous researches reported an obvious negative correlation between USP14 expression and survival time of patients with non-small-cell lung cancer." (PMID 34420039, 2021).
atherosclerosis (10 papers, 2020 to 2025). A disease characterized by the build-up of fatty material and calcium deposition in the arterial wall resulting in partial or complete occlusion of the arterial lumen. "Conversely, USP14 deficiency regulates the posttranslational modifications of scavenger receptor CD36 to suppress atherosclerosis development and cardiac hypertrophy by regulating GSK-3β phosphorylation and mediates lipopolysaccharide-induced inflammation." (PMID 38909015, 2024). "Aberrant expression of USP14 has close association with multiple diseases, including atherosclerosis." (PMID 38424494, 2024). "Conversely, inhibiting USP14 facilitates IL-4/IL-13-induced anti-inflammatory M2 macrophage polarization, alleviating inflammation in atherosclerosis." (PMID 40376148, 2025). "Studies have found that USP14 expression is downregulated in atherosclerosis patients and endothelial cells stimulated by oxidised low‐density lipoprotein." (PMID 40988122, 2025). "Here, USP14 level was found to be positively correlated with USF1 level in the clinical samples of atherosclerosis." (PMID 38424494, 2024). "Respectively, in atherosclerosis patients, USP14 is observed to be downregulated in ECs, and it inhibits the inflammatory response in ECs." (PMID 38322269, 2024). "Collectively, these data demonstrated that activating Smad2/3 pathway was considered the downstream of USP14/NLRC5 axis to contribute to atherosclerosis progression by promoting EndMT in vivo." (PMID 38424494, 2024). "Taken together, we uncover a USF1/USP14/NLRC5/Smad2/3 axis that drives atherosclerosis progression via inducing EndMT." (PMID 38424494, 2024). "Our findings indicate the contribution of the USF1/USP14/NLRC5 axis to atherosclerosis development via promoting EndMT, which provide effective therapeutic targets." (PMID 38424494, 2024). "As the only USP family that can reversibly bind the 19S regulatory particle of the proteasome, USP14 plays a critical role in regulating the inflammation progression in various diseases, such as lung injury and atherosclerosis." (PMID 37269080, 2023). "Given that smooth muscle cells exert this phenotypic switch in atherosclerotic lesions, USP14 in smooth muscle cells appears to trigger atherosclerosis." (PMID 36834633, 2023). "USP14 also has diverse influences on atherosclerosis development, depending on the cells that express it: USP14 in smooth muscle cells inhibits atherosclerosis, and USP14 in epithelial cells represses atherosclerotic inflammation." (PMID 36834633, 2023). "Since the formation of the foam cells is the most important and the initial stage in the development of atherosclerosis, we sought to study the effect of USP14 inhibition on foam cell formation." (PMID 31970862, 2020). "Our study describes a possible mechanism how USP14 participates in the pathologic processes of atherosclerosis and provides a new target for clinical therapy in atherosclerosis." (PMID 31970862, 2020). "In the future, USP14 may emerge as a promising therapeutic target for controlling inflammation and treating atherosclerosis, offering new avenues for disease intervention." (PMID 40376148, 2025). "Additionally, USF1 transcriptionally activated USP14 to drive atherosclerosis by promoting EndMT through the NLRC5/Smad2/3 axis." (PMID 40413536, 2025). "Undoubtedly, USP14 plays a crucial role in the pathogenesis of atherosclerosis." (PMID 40376148, 2025). "The role of USP14 in atherosclerosis is currently under debate." (PMID 36834633, 2023). "Furthermore, infection with Usp14-expressing adenovirus halted the progression of atherosclerosis in apolipoprotein E (Apoe) KO mice." (PMID 36834633, 2023). "Additionally, in vivo experiments confirmed USP14's inhibitory effect on atherosclerotic lesions, suggesting that USP14 may be a potential target for treating atherosclerosis." (PMID 40988122, 2025). "Thus, USF1 exacerbated atherosclerosis progression by transcriptional activation of USP14." (PMID 38424494, 2024).
atherosclerosis (continued). "In this study, we demonstrated that USF1 transcriptionally activated USP14 to restrain NLRC5 degradation, which prompted atherosclerosis by facilitating EndMT by activation of Smad2/3 pathway." (PMID 38424494, 2024). "In summary, our results suggested that the inhibition of USP14 decreases foam cell formation by down‐regulating CD36‐mediated lipid uptake and provides a potential therapeutic target for atherosclerosis." (PMID 31970862, 2020). "Of note, as predicted by JASPAR database, USF1 can directly bind to USP14 promoter, providing possibility that USF1 might influence atherosclerosis progression via transcriptional modulation of USP14." (PMID 38424494, 2024). "USP14 depletion was demonstrated to restrain foam cell formation through inhibiting CD36-mediated lipid uptake, which is considered as a therapeutic strategy for atherosclerosis." (PMID 38424494, 2024). "Likewise, USP20 in hepatocytes and USP14 in smooth muscle cells exacerbate atherosclerosis, whereas USP20 in smooth muscle cells and USP14 in endothelial cells improve disease outcomes." (PMID 36834633, 2023). "USP14 inhibitor IU1 significantly increases CD36 ubiquitination and stabilizes CD36 protein by removing the polyubiquitin chains, decreasing foam cell formation by downregulating CD36-mediated lipid uptake, and providing a potential therapeutic target for atherosclerosis." (PMID 35301297, 2022).
lung adenocarcinoma (10 papers, 2013 to 2023). A carcinoma that arises from the lung and is characterized by the presence of malignant glandular epithelial cells. "Previous studies demonstrated increased USP14 mRNA expression levels in lung adenocarcinoma and the association of higher USP14 levels with worse prognosis." (PMID 37035133, 2023). "We found that USP14 was significantly (p-value cut-off 0.01) up-regulated in both lung adenocarcinoma (LUAD) and lung squamous cell carcinoma (LUSC) compared to normal lung tissue." (PMID 32887472, 2020). "The results showed that the expression of USP14 increases significantly in non-small cell lung cancer (NSCLC) tissue, particularly in lung adenocarcinoma tissues, and over-expression of USP14 promotes tumor cell proliferation." (PMID 30319415, 2018). "The level of USP14 was significantly correlated with overall survival of lung adenocarcinoma patients." (PMID 23702845, 2013). "Here we studied the expression and function of USP14 in NSCLC, its relationship with clinicopathological features, and its prognostic value for the survival of patients with lung adenocarcinoma." (PMID 23702845, 2013). "However, to the best of our knowledge, there is as yet no report demonstrating a role for USP14 in lung adenocarcinoma." (PMID 23702845, 2013). "Although SLFN12 was previously reported to act through modulating proteasomal and USP14 and USCHL5 deubiquitylase activity, this did not appear to be the case in lung adenocarcinoma cells." (PMID 32987632, 2020).
colon cancer (8 papers, 2014 to 2026). "In vivo, combining a USP14 inhibitor with an anti-PD-1 antibody synergistically enhanced immunotherapy efficacy, suppressed tumor progression, and improved survival in a mouse colon cancer model." (PMID 42058892, 2026). "Using an inducible USP14 knockout system in colon cancer cells, we found that USP14 depletion impedes cellular proliferation, induces cell cycle arrest, and leads to a senescence-like phenotype." (PMID 38844605, 2024). "In NSCLC and colon cancer cell lines, USP14 inhibition has been shown to induce cell death by targeting Wnt/β-catenin signaling pathway." (PMID 32887472, 2020). "A strong correlation has been found between the levels of β-catenin and USP14 by tissue microarray analysis of colon cancers, suggesting an oncogenic role of USP14 by the enhancement of Wnt/β-catenin signaling." (PMID 32549302, 2020). "Tissue microarray analysis of colon cancer has consistently revealed a strong correlation between the levels of USP14 and β-catenin, which suggests an oncogenic role for USP14 via the enhancement of Wnt/β-catenin signaling." (PMID 25972356, 2015). "In conclusion, USP14 loss in colon cancer cells induces a transient quiescent cancer phenotype not replicated by pharmacologic inhibition of its deubiquitinating activity." (PMID 38844605, 2024). "Moreover, it has been shown that USP14 regulates Wnt/β-catenin signaling pathway by regulating Deshevelled (Dv1) protein in colon cancer." (PMID 31653087, 2019). "In order to gain insight into the mechanisms through which the USP14/UCHL5 inhibitor b-AP15 kills cells, we compared the effect of this compound on HCT116 colon cancer cells and non-malignant hTERT-RPE1 cells." (PMID 25286379, 2014).
leukemia (7 papers, 2017 to 2024). A malignant (clonal) hematologic disorder, involving hematopoietic stem cells and characterized by the presence of primitive or atypical myeloid or lymphoid cells in the bone marrow and the blood. "According to recent studies, b-AP15 and VLX1570 could also be a potential therapy for leukemia and WM by inhibiting 19S proteasome-associated DUBs such as USP14/UCHL5 and inducing tumor-cell apoptosis." (PMID 32354135, 2020). "Specifically, it was reported that upregulated expression of USP14 is associated with leukemia and may be implicated in apoptosis." (PMID 32354135, 2020). "It was reported that zinc pyrithione-metal chelate (ZnPT) induces apoptosis in primary cancer cells from leukemia patients by targeting USP14 and inhibiting the growth of xenograft tumors in mice." (PMID 38531846, 2024). "This study demonstrated that the USP14/UCHL5 inhibitors b-AP15 and AUR effectively inhibited the K48-mediated deubiquitination of ubiquitin bound to FLT3 in leukemia cells with FLT3-ITD mutations." (PMID 39408703, 2024). "Apoptosis induction in leukemia cells through USP14 inhibition has been previously documented; however, this is the first study to identify a specific mechanism by which USP14/UCHL5 inhibition induces apoptosis in FLT3-ITD-positive AML cells or in primary FLT3-ITD-positive AML cultures." (PMID 39408703, 2024). "For instance, the deubiquitinating activity of USP9X regulates proper targeting and association of Survivin and Aurora B proteins to the centromeres, USP39 regulates the mRNA splicing of Aurora B, while USP14 was reported to regulate the stability of Aurora B in leukemia cells." (PMID 34445214, 2021). "In a recent study, USP14, one of the proteasome-associated deubiquitinating enzymes, was found responsible for AURKB stabilization and AURKB stabilization by ectopic expression of USP14 prevented the apoptosis induced by chemotherapeutic drugs in leukemia cells." (PMID 30206236, 2018). "First, we investigated the effects of b-AP15, a specific inhibitor of USP14/UCHL5, and AUR, a gold compound with similar inhibitory activity, on the cell cycle of leukemia cell lines." (PMID 39408703, 2024). "A specific inhibitor of USP14, b-AP15, can significantly increase the apoptosis of leukemia cells." (PMID 33498168, 2021).